MCM5 (minichromosome maintenance complex component 5)
Diseases named in the same sentence as MCM5 in open-access papers (continued):
Sharing a sentence is not in itself a finding about the gene and the disease.
microcephaly (1 paper, 2022). A congenital or acquired developmental disorder in which the circumference of the head is smaller than normal for the person's age and sex. "Similar to the undergrown CNS observed in Drosophila Mcm5 mutants, 43% of human Meier-Gorlin patients display microcephaly." (PMID 35737938, 2022).
oral cancers (1 paper, 2015). "In a recent study, increases in MCM5 protein as human oral cancers (including tongue cancer) progress were reported." (PMID 26110572, 2015).
parasitic infection (1 paper, 2023). "Sufficient information on the role of MCM5, ATN1, SCNA and STX1A genes in the context of parasitic infection is not available." (PMID 37761803, 2023).
prostatitis (1 paper, 2010). An infectious or non-infectious inflammatory process affecting the prostate gland. "Notably, prostatitis was associated with an elevated Mcm5 signal." (PMID 20648010, 2010).
rectal adenocarcinoma (1 paper, 2020). "MCM5 was higher 1.240-fold in colon and 1.213-fold in rectal adenocarcinoma samples than in normal tissues." (PMID 32597491, 2020).
retinoblastoma (1 paper, 2018). A malignant tumor that originates in the nuclear layer of the retina. "Apart from cellular stress response proteins, cell cycle proteins such as CDK1, CDK11, MCM2, MCM3, MCM5, and CCNB1 were also found to be hyperphosphorylated in retinoblastoma, implicating accelerated cell cycle progression." (PMID 29914080, 2018).
sarcoma (1 paper, 2021). A usually aggressive malignant neoplasm of the soft tissue or bone. "We found that except for MCM1, all other MCM factors had higher expression levels in sarcoma than in normal tissues (p < 0.05 for MCM2, MCM4, MCM5, MCM6 and MCM7)." (PMID 34239894, 2021).
serous ovarian cancer (1 paper, 2021). "The serous ovarian cancer dataset indicated that the percentages of DNA alterations of MCMs were 5% (MCM2), 4% (MCM3), 5% (MCM4), 2.6% (MCM5), 1.2% (MCM6), and 5% (MCM7)." (PMID 34178669, 2021).
Shwachman-Bodian-Diamond Syndrome (1 paper, 2023). "In particular, MCM2 (minichromosome maintenance complex 2), MCM5, MCM7, multiple copies in T-cell lymphoma-1, RPS25 ribosomal protein S25, and Shwachman-Bodian-Diamond Syndrome were successfully confirmed." (PMID 37391046, 2023).
viral infection (1 paper, 2017). "The repression of MCM2, MCM3, MCM5, and MCM7 was associated with viral infection previously, but detailed functional studies have not been carried out." (PMID 28912786, 2017).
tumor (52 papers, 2004 to 2025). "Consistent with this notion, overexpression of MCM5 also associates with tumor stages, which appears to be potential diagnostic and prognostic markers in thyroid cancer, ovarian cancer, bladder cancer, and renal cell carcinoma." (PMID 36776764, 2023). "The complex gene expression profile of all-low tumor (ALDH6A1 + TFF2 + MCM5) was strongly associated with ORR in the Bevacizumab qPCR set (ORR 85.7%, p = 0.007), but not in the Control set (ORR 36.4%, p = 0.747)." (PMID 24555920, 2014). "Interestingly, at non-tumor visits the urinary content of especially hTERT (p = 0.0001) and MCM5 (p = 0.02) were significantly associated with subsequent tumour recurrence." (PMID 21106093, 2010). "Our study demonstrated that TCF3 suppressed CRC development by modulating DNA replication through repressing MCM2 and MCM5 transcription, providing a novel mechanistic insight into its tumor-suppressive function." (PMID 40998798, 2025). "Specifically, overexpression of ESPL1 and MCM5 has been significantly correlated with advanced tumor stages and disease progression, underscoring their potential utility as biomarkers for predicting clinical outcomes." (PMID 41226409, 2025). "MCM5 is a chromatin-binding protein that serves as a diagnostic marker for CRC, regulating tumor cell proliferation and cell cycle progression." (PMID 38384287, 2024). "MCM5‐overexpressing A549 cells gained ability to penetrate into neighboring subcutaneous tissue in formed tumor xenografts and exhibited much stronger metastatic bioluminescent signals." (PMID 37171793, 2023). "Among the selected genes, only RPA1, MCM5 and FEN1 had significantly (p < 0.05; q < 0.05) higher mRNA expression in BRAFV600E-mutated tumor samples in comparison with unaltered group." (PMID 37106808, 2023). "Inhibiting the IGF2BP3/MCM5/NICD1 axis impairs the tumor cell plasticity and potently abrogates distant metastasis of LUAD cells." (PMID 37171793, 2023). "For example, ERβ suppresses the expression of mini chromosome maintenance complex component 5 (MCM5), a DNA replication licensing factor that is involved in tumor cell growth." (PMID 35632722, 2022). "As expected, genes involved in cell-cycle and nucleotide metabolism, such as DUT and MCM5, were required for tumor growth." (PMID 32579974, 2020). "In normal epithelium MCM5 expression is restricted to the cells in the basal proliferative compartments, however in the presence of a tumour MCM5 positive cells are present at the surface epithelium and are shed into bodily fluids." (PMID 33059604, 2020). "There were 15 genes, including ESPL1 and MCM5, that showed relativity (P < 0.05) with tumor stage changing." (PMID 29884122, 2018). "Mechanism dissection found that targeting ERβ suppressed the expression of minichromosome maintenance complex component 5 (MCM5), a DNA replication licensing factor that is involved in tumor cell growth." (PMID 25277204, 2014). "The Odds Ratio for response for the all-low tumor (ALDH6A1 + TFF2 + MCM5) profile versus any other ALDH6A1 + TFF2 + MCM5 profile was 15 (p = 0.018) in the Bevacizumab qPCR set but only 0.72 (p = 0.63) in the Control set." (PMID 24555920, 2014). "No positive correlation is found between expression levels of MCM5 with increasing tumor stages (Spearman’s rho = −0.308, p = 0.078)." (PMID 23874974, 2013). "MCM5 shows significant up-regulation in primary tumor (0.206±0.152, median = 0.27, p = 0.018) and cell lines (0.305±0.05, median = 0.32, p = 0.0001) compared to normal (0.128±0.098, median = 0.12)." (PMID 23874974, 2013). "Like other replication factors, Mcm5 is considered as a marker for tumor proliferation, thus it will be interesting to study its putative role in promoting the unrestricted metacestode proliferation encountered in murine alveolar echinococcosis of the liver." (PMID 20368974, 2010). "Here we evaluated the diagnostic value of measuring the urinary content of hTERT, MCM5, PPP1CA, and SENP1 mRNAs for detection of tumor recurrence." (PMID 21106093, 2010).
tumor (continued). "The Cuzick extension of the Wilcoxon's rank sum test confirmed the presence of a significant trend of increasing MCM-2 and MCM-5 expression with increasing tumour stage (P=0.0100 and 0.0300, respectively)." (PMID 17940502, 2007). "Microchromosome maintenance protein 5 (MCM5) is a crucial factor in DNA replication, located at the basal layer of the epithelium in normal tissues, which would extend to the whole epithelial layer in the tumor situation." (PMID 35804953, 2022). "However, the exact role of MCM5 in the tumor immune microenvironment requires further investigation." (PMID 35360518, 2022). "Moreover, we detected that the expression of ESPL1 and MCM5 were negatively correlated with tumor stage progression." (PMID 29884122, 2018). "The trend for higher grade and stage tumours to exhibit higher Mcm5 levels could provide a useful predictive clinical role e.g. to target imaging and rigid cystoscopic diagnostic procedures for high risk patients identified by urinary Mcm5." (PMID 22792272, 2012). "Therefore, transcriptional promotion of MCM5 by MTA2 may be a key mechanism in regulating GC tumor growth." (PMID 36741260, 2023). "However, the exact role of MCM5 in the tumor immune microenvironment requires further exploration." (PMID 35360518, 2022). "In addition, ESPL1 and MCM5 expression were negatively correlated with tumor stage progression, and regression analysis indicated that ESPL1 and MCM5 were correlated to tumor stages (Pearson correlation = − 0.25713; P = 9.54E-05 and Pearson correlation = − 0.13982; P = 0.023, respectively)." (PMID 29884122, 2018). "Furthermore, hTERT and MCM5 levels predicted subsequent tumor recurrences." (PMID 21106093, 2010). "Interestingly, ulcerative lesions gave a signal, but with an amplitude below that generated by tumours, most likely reflecting reparative growth with exposure of the stem-transit compartment to luminal secretions and the shedding of reactive Mcm5-positive cells." (PMID 15266314, 2004). "The tumor group exhibited statistically significant differences in SPP1, LYZ, and MCM5 expression levels in NK/T cells, myeloid cells, epithelial cells, and other cells compared to the healthy control group." (PMID 41384115, 2025). "For example, ERβ has been shown to regulate minichromosome maintenance complex component 5 (MCM5), a key regulator of DNA replication and cell proliferation, suggesting that ERβ activation contributes to tumor progression." (PMID 40806474, 2025). "IHC staining of tumor tissues acquired on the day of sacrifice showed decreased MCM2, MCM5, BrdU and MKI67 levels in TRIM21 knockdown groups, contrasting with elevated TCF3 levels." (PMID 40998798, 2025). "Decreased expression of Mini-chromosome Maintenance Complex Component 3 (MCM3), MCM4, MCM5 and MCM7 inhibited DNA replication and proliferation of various tumor cells." (PMID 40998798, 2025). "The recruitment of m6A modification by IGF2BP3 on minichromosome maintenance complex component 5 (MCM5) mRNA can trigger EMT and enhance the adaptability of LUAD cells via m6A‐dependent overactivation of the Notch signal, ultimately driving tumor metastasis." (PMID 38706740, 2024). "Our results verify chemotherapy sensitizing and anti-tumor function of miR143-3p in TNBC and we also identified MCM5 as a new target of miR143-3p." (PMID 34162418, 2021). "Recent studies have reported that tumor-suppressive miRNAs negatively regulate the expression of MCM family genes (e.g., MCM2 is targeted by miR-31 and MCM5 is targeted by miR-885-5p and miR-362-3p)." (PMID 31514295, 2019). "In the pathway in cell cycle, we found that the expression of Ccna2, Cdc25a, Mcm3, Mcm6, Ccnb2, Mcm5, Cdk1, Gadd45a were down-regulated in the MMQ tumor stem-like cells." (PMID 28163656, 2017). "Bcl2, VEGFA, PTEN, Jun, Fos, APC2 were up-regulated and Ccna2, Cdc25a, Mcm3, Mcm6, Ccnb2, Mcm5, Cdk1, Gadd45a, Myc were down-regulated in MMQ tumor stem-like cells group." (PMID 28163656, 2017).
tumor (continued). "In pathway in cancer and cell cycle, Bcl2, VEGFA, PTEN, Jun, Fos, APC2 were up-regulated and Ccna2, Cdc25a, Mcm3, Mcm6, Ccnb2, Mcm5, Cdk1, Gadd45a, Myc were down-regulated in the MMQ tumor stem-like cells." (PMID 28163656, 2017). "Among those, we identified MCM5, STMN1, RCL1 and C9ORF114, proteins that reflect the high proliferation rate of these tumours." (PMID 26725330, 2016). "Tumor tissue samples from patients with unfavorable PFS status were found to overexpress four out of the five genes (AGR2, ALDH6A1, TFF2, MCM5) and underexpress KLF12." (PMID 24555920, 2014). "A significant decrease in the amplitude of the Mcm5 and NMP22 signal with lower tumour grade and stage was observed, in keeping with the increasing false negative rates observed for these groups." (PMID 22792272, 2012). "The median MCM-2 and MCM-5 LIs were significantly higher in adenocarcinomas (20 and 24%, respectively) compared to LMP tumours (5 and 6%, respectively) (Mann–Whitney U-test, P<0.0001 for both associations)." (PMID 17940502, 2007). "Thus, the ‘improved’ sensitivity of MCMs as markers of proliferating cells could reside in the identification of differentiating cells, which is consistent with our finding that the highest difference among MCM-5 and Ki-67 is recorded within the grade I (i.e. the well-differentiated) tumours." (PMID 17940502, 2007). "Interestingly, KIF20A is a well-known tumor antigen, and MCM3 and MCM5 are critical controllers for regulating cell cycles." (PMID 37884996, 2023). "We found a significant increase in MCM2 (3.5 fold), MCM3 (3.1 fold), MCM4 (4.3 fold), MCM5 (3.8 fold), MCM6 (3.5 fold), MCM7 (3.0 fold) and MCM10 (3.6 fold) expressions in tumor tissues (the average fold value of three grades) compared to the normal brain controls." (PMID 25046975, 2014). "The discrepancy of correlation of MCM2, MCM5 and MCM7 may be due to a very small sample size in tumor stage I (N = 06)." (PMID 23874974, 2013). "Interestingly, as a cell cycle pathway member, MCM5 was highly expressed in GC tumor tissue relative to non-tumor tissue and positively correlated with MTA2." (PMID 36741260, 2023). "Persistence of elevated Mcm5 signals in the urine sediments of treated patients suggests that there has been no significant reduction in tumour cell volume, and this may contribute to relapse after such medical therapeutic interventions." (PMID 20648010, 2010). "Interestingly hTERT, MCM5, and PPP1CA were positive in all 7 samples with atypical cells grade 2 or grade 3 that were diagnosed as non-recurrent because no tumors were found at cystoscopy; however, all were diagnosed with a tumor in the follow-up period." (PMID 21106093, 2010). "MCM5 (40%), MCM6 (45.5%) and MCM9 (25%) were moderately higher in tumor tissues than in normal tissues, and MCM10 was negative in most (91.7%) tumor tissues." (PMID 34859821, 2021). "Tumor cells did not expressed most of the markers tested, including PDL1, with the notable exception of MCM5, IDO, B7H3 and Axl." (PMID 31959856, 2020). "We found significant differences in urinary content of hTERT (p < 0.001), SENP1 (p < 0.001), MCM5 (p < 0.001), and PPP1CA (p < 0.001) transcripts, when comparing urine samples from patients with and without tumor present in the bladder." (PMID 21106093, 2010).
cancer (41 papers, 2004 to 2025). A tumor composed of atypical neoplastic, often pleomorphic cells that invade other tissues. "Since MCM5 which is essential for the initiation of DNA replication has been reported to associated with cancer cell proliferation and metastasis, we focused on the role of MCM5 in DDX21-dependent CRC regulation." (PMID 37029300, 2023). "Cancer patients with a higher expression of MCM5 and MCM7 were significantly linked with poor overall survival." (PMID 37384298, 2023). "In addition, overexpression of MCM5, identified here as associated with maternal toenail arsenic levels, has previously been identified in a variety of human cancers." (PMID 26771251, 2016). "A reduction in the level of some MCM proteins in human cancer cells (MCM5 in U20S cells or MCM3 in Hela cells) causes a rapid increase in the level of DNA damage under normal conditions of cell proliferation and a loss of viability when the cells are subjected to replication interference." (PMID 22102875, 2011). "This study elucidates a critical role of m6A modification in shaping cancer cell plasticity via the IGF2BP3/MCM5/Notch axis." (PMID 37171793, 2023). "The genes in Cluster-1, such as MCM2, STAT1, BRCA1, and MCM5, are overexpressed in the cancer samples." (PMID 37925498, 2023). "A high level of MCM5 has been found in multiple cancers, including colon cancer, cervical cancer, and thyroid cancer." (PMID 34178669, 2021). "The MCM5 level was higher in 46 cancer datasets and lower in two cancer datasets than in normal tissue datasets." (PMID 34178669, 2021). "MCM5 levels were tested in samples (urine sediment, plus vaginal swab or tampon) from all 67 cancer patients and all 58 control patients." (PMID 33059604, 2020). "Analysis from CHAT revealed that BIRC5, E2F2, KIF2C, FOXM1, and MCM5 were mainly involved in sustaining proliferative signaling in cancer development, with npmi values of 0.15, 0.222, 0.168, 0.218, and 0.157, respectively." (PMID 31579605, 2019). "First, our RNA-seq showed CARMN may potentially regulated many cancer-related genes and pathways in which we only explored the most enriched pathway DNA replication and DNA replication related gene MCM5." (PMID 34162418, 2021). "MCM5 was well documented to play a role in tumorigenesis and cellular processes in various cancers." (PMID 34408205, 2021). "In contrast, Mcm5 detection can be regarded as a cancer-specific test." (PMID 20648010, 2010). "Indeed, in our study, strong correlations emerged between MCM-2 or MCM-5 LIs and the conventional proliferation index Ki-67, which remained even after stratification of our cases into borderline or carcinoma categories." (PMID 17940502, 2007). "Furthermore, MCM5 is frequently upregulated in various human cancers." (PMID 36741260, 2023). "IGF2BP3 recognizes m6A‐modified MCM5 mRNA to promote their stability and upregulate MCM5 protein levels, leading to p‐EMT‐induced cancer cell plasticity." (PMID 37171793, 2023). "Cluster 4 showed high expression of cell cycle‐related genes for markers such as PCNA, MCM5, MKI67, STMN1, and CDK1, probably owing to the immune response to cancer neo‐epitopes." (PMID 33513276, 2021). "Of the 10 proteins, the preceding text showed that some studies identified RRM2, PLOD2, MKI67, MCM5, and CKD1 promoted cancer progression and FBP1, FBP2, ENO3, GPD1, and ASS1 inhibited cancer progression, which was consistent with our results." (PMID 33200655, 2020). "The diagnostic values of the individual MCM subunits were identified in various cancers including MCM2 in gastric cardiac cancer and salivary gland tumor, MCM5 in esophageal cancer, MCM7 in meningiomas, and MCM10 in breast cancer." (PMID 32089988, 2020).
cancer (continued). "In addition, CDC20, CDK4, MCM6, MAD2L1, MCM2 and MCM5 were leading genes intersecting in these four pathways, and a positive correlation between mRNA expression and LACTB was observed in most normal and cancer tissues." (PMID 33507917, 2021). "While the expression of MCM5 has been accurately reported in other cancers, it has not been done so in BC." (PMID 34475953, 2021). "A previous study showed that the high expression of MCM2, MCM5, and MCM7 might indicate a poor prognosis of cancer." (PMID 34413873, 2021). "The researchers concluded that high expression of MCM2, MCM5, and MCM7 might be prognostic indicators for poor outcomes in cancers." (PMID 32089988, 2020). "Furthermore, we have identified additional genes downregulated by Cl-amidine, including MKI67, MCM5, and MCM2, each with known functions in cancer progression." (PMID 23110523, 2012). "Sections from 17 benign lesions and 55 carcinomas were immunostained with anti DMBT1 antibody (DMBTh12) and sections from 36 samples, were double-stained also with anti MCM5, one of the 6 pre-replicative complex proteins with cell proliferation-licensing functions." (PMID 15301691, 2004). "This hypothesis is validated by our study that, since MCM5 is a phase separation-specific target of DDX21, we can suppress cancer metastasis by inhibiting MCM5 expression without disrupting DDX21 phase separation." (PMID 37029300, 2023). "Furthermore, certain cell cycle–related proteins, including TOP2A, PCNA, MCM2, MCM4, MCM5, MCM6, and MCM7, have also been reported to facilitate cancer cell proliferation, and the enhanced expression of these cell cycle–related proteins may contribute to uncontrolled ESCC cell proliferation." (PMID 38652547, 2024). "However, it is now widely accepted that many high grade serous cancers arise in the fallopian tube rather than the ovary and thus the MCM5 test may have use in at least some of these cancers." (PMID 33059604, 2020).